BCL2 (BCL2 apoptosis regulator)
Diseases named in the same sentence as BCL2 in open-access papers (continued):
Sharing a sentence is not in itself a finding about the gene and the disease.
cervical carcinoma (continued). "In HeLa cervical cancer cells, luteolin increased the expression of various pro-apoptotic proteins, including BAX, BAD, BID, APAF1, TRADD, FAS, FADD, and caspase-3 and -9, but the expression of anti-apoptotic proteins, such as BCL-2 and MCL-1, decreased." (PMID 36142874, 2022). "In addition, cervical cancer cell apoptosis was induced through an increase in BAX and a decrease in Bcl-2 in an in vivo tumor model." (PMID 36142874, 2022). "The results indicate that GRg5, in combination with PTX, augments Bax and cleaved caspase-9 and simultaneously diminishes Bcl-2, which confirms the efficacy of GRg5 aided PTX to control PTX resistant cervical cancer cells through a mitochondrial-mediated intrinsic apoptotic pathway." (PMID 35885925, 2022). "BCL-2 is an anti-apoptotic molecule and the expression of BCL-2 and BAX might correspond to disease stage progression or cell radiosensitivity in cervical cancer." (PMID 34350111, 2021). "Moreover, RAC1 inhibits apoptosis by binding to and stabilizing antiapoptotic BCL-2 family proteins (BCL-2 and MCL1) in colon cancer, cervical cancer, and B-cell lymphoma." (PMID 34172833, 2021). "In conclusion, the present study used immunohistochemical staining to validate how the expression of BCL-2, HER2, CD133, CAIX, and ERCC1 could predict chemoradioresistance and disease recurrence in patients with early cervical cancer." (PMID 34350111, 2021). "S. flavescens inhibits cervical-cancer-cell proliferation and metastasis and induces apoptosis by inhibiting the AKT/mTOR signaling pathway; reducing the expression of Bcl-2, cyclin A and MMP2; blocking the G2/M phase cell cycle; and stimulating Bax and E-calmodulin." (PMID 34680171, 2021). "Although the combination of ABT-737 with arsenic trioxide enhances cell apoptosis, their unique actions on cervical cancer cells were explored in other routes rather than the direct inhibition of Bcl-2." (PMID 31906234, 2019). "Employing the same technique, expression levels of survivin (inhibitor of apoptosis), BCL-2 and KAI 1 (tumour metastases suppressor protein) were investigated in normal cervix, chronic cervicitis, cervical intraepithelial neoplasia (CIN) and cervical cancer." (PMID 29580266, 2018). "Apoptosis protein analysis of Bcl-2, Bax, and Caspase-3 protein was determined by Western blot analysis after overnight incubation with treatment of FSK-2 μM, FSK-5 μM, and FSK-10 μM of Forskolin on HeLa cervical cancer cells." (PMID 30558287, 2018). "Moreover, the active form of STAT3, phospho-STAT3 (p-STAT3), and two identified downstream genes of STAT3, BCL-2 and MMP-2, were consistently suppressed, which demonstrated that STAT3 is a target gene of miR-29b in cervical cancer cells." (PMID 28122338, 2017). "So we detected the regulatory effect of PI3K/AKT, IκBα and IKK signaling on the expression of apoptosis related genes Bax and Bcl-2, in order to make sure whether STC1 works through the PI3K/AKT signaling to regulate cell apoptosis of cervical cancer cells." (PMID 28545028, 2017). "In terms of mechanism research, increased CDKN1A expression and Bax/Bcl-2/caspase-3 signaling pathway might be involved in the G2/M phase arrest and increased apoptosis in RIF1-silenced cervical cancer cells." (PMID 29291010, 2017). "Cervical cancer cells upregulate Bcl-2 when treated with a non-cytotoxic concentration of cisplatin, which when silenced, effectively enhanced cisplatin sensitivity, and therefore significantly induced apoptosis." (PMID 26474854, 2015). "Another example is BCL2, which contains the reverse complements to miR-15a-5p and miR-181c in the 3’UTR, responds to anthracycline combination (ATC) chemotherapy, and plays an important role in cervical cancer progression." (PMID 24405714, 2014).
cervical carcinoma (continued). "In the 24 effective chemotherapy cases, there was no significant decline of the bcl-2 positive expression after chemotherapy, suggesting that bcl-2, was not involved in the response of cervical cancer tissue to Taxol either." (PMID 24774218, 2014). "Our findings demonstrate that cepharanthine significantly induces mitochondrial apoptosis in human cervical cancer cells both in vitro and in vivo, as evidenced by the increased expression of cleaved PARP-1 and cleaved caspase-3 proteins, along with an elevated Bax/Bcl-2 ratio." (PMID 41300481, 2025). "However, overexpressed KHDC1A induces endoplasmic reticulum-dependent apoptosis in human cervical cancer cells (Hela) in vitro, and induces apoptosis independent of the Bcl-2 pathway in 293 T cells and mouse T cells in vivo." (PMID 36734243, 2023). "DET (4.14 μg/mL; 48 h) downregulated Bcl-2 and Bcl-XL and upregulated Bax at mRNA, thus altered the Bax/Bcl-2 ratio at the mRNA level with the activation of caspase-9, -7, and -3, released cytochrome c in cytosol, and induced PARP cleavage in cervical carcinoma SiHa cells." (PMID 35408483, 2022). "Therefore, to determine the utility of CD34 and Bcl-2 expression as predictive biomarkers, we investigate the relationship between the expression of two biomarkers before NACT and the efficacy of NACT in cervical cancer." (PMID 33392721, 2021). "Our study first provided that the combination of SNX-2112 with TRAIL could enhance cancer cell death by downregulating antiapoptosis proteins, including Bcl-2, Bcl-XL, and FLIP, and elucidate the mechanism by which SNX-2112 sensitizes TRAIL to apoptosis in cervical cancer cells." (PMID 31019655, 2019). "HeLa cervical carcinoma, MDA-MB-231 breast adenocarcinoma, Saos-2 osteosarcoma, and Panc-1 pancreas ductal carcinoma cells all displayed statistically significant reductions in TAF6δ-dependent apoptosis when the mitochondrial pathway was blocked via overexpression of anti-apoptotic Bcl-2 proteins." (PMID 29358700, 2018). "Furthermore, we confirmed that miR‐143‐5p inhibited the progression of the cervical cell cycle, proliferation, migration, and invasion, and inhibited cervical cancer cell apoptosis through downregulation of the protein expression levels of ELK1, p‐ELK1, C‐fos, Cyclin D1, and Bcl‐2." (PMID 28544557, 2017). "Here we show that a previously non-cytotoxic concentration of cisplatin becomes toxic to cervical cancer cells and provides conceptual evidence to suggest that lower dosages of cisplatin may be a viable approach to treatment when combined with Bcl-2 silencing." (PMID 26474854, 2015). "Due to activation of STAT3 and the over-induction of antiapoptotic genes found on cervical cancer cell lines after PRL stimulation, we decided to inhibit the STAT3 activation using the inhibitor AG490; which resulted in an impaired induction of Bcl-xl, Bcl-2, survivin and Mcl-1." (PMID 26346346, 2015). "While previous data suggest that Beclin-1 does not affect the anti-apoptotic activity or localization of Bcl-2, this finding may be context and cell type-specific; these studies were performed in HeLa cervical carcinoma cells and mouse embryonic fibroblasts." (PMID 23452820, 2013). "However, we observed that Bcl-XL and Bcl-2 proteins were not related with resistance to CIS in cervical cancer cells, since the expression of Bcl-XL was even higher in parental SiHa cells than in resistant SiHa cells, whereas Bcl-2 expression was similar in both cell lines." (PMID 33680921, 2020). "Although Bcl-2 are closely related to the stage and survival of cervical cancer, its expression before NACT is not a predictor of NACT in cervical cancer." (PMID 33392721, 2021).
cervical carcinoma (continued). "The positive CD34 expression before NACT may serve as a predictive biomarker for NACT of cervical cancer, but the pre-NACT expression of Bcl-2 is not an independent predictor." (PMID 33392721, 2021).
glioblastoma (206 papers, 2002 to 2026). The most malignant astrocytic tumor (WHO grade IV). "Apoptosis in glioblastoma has been reported to be closely associated with the abundance of β-catenin, cyclin D1 (a known β-catenin-regulated gene), and Bcl-2." (PMID 37175205, 2023). "MiR-125b-2 induced temozolomide resistance in glioblastoma stem cells was associated with downregulation of Bax and upregulation of Bcl-2." (PMID 35582140, 2019). "NAG-1 overexpression caused decreased Bcl-2 expression, increased Bax expression, and elevated level of cytosolic cytochrome c in glioblastoma cells." (PMID 24759784, 2014). "Overexpression of miRNA-21 has also been associated with glioblastoma resistance to temozolomide, the standard first-line treatment, by impacting the balance between the pro-apoptotic Bax protein and the anti-apoptotic Bcl-2, as well as by influencing Caspase 3 activity." (PMID 39851519, 2025). "TMEM176A in glioblastoma can inhibit Bcl2 expression and cause apoptosis." (PMID 36302939, 2022). "Glioblastoma tumors express high levels of anti-apoptotic BCL2 family proteins such as Bcl-2 and Bcl-xL, which may cause glioblastoma cells to resist apoptosis." (PMID 32770097, 2020). "These suggest that reducing total protein amount in KPNB1-deficient glioblastoma cells by translation inhibition via mechanisms like ER stress aims at restoring proteostasis, whereas chronic ER stress upregulates pro-apoptotic Bcl-2 proteins and induces apoptosis." (PMID 29520102, 2018). "Also, miRNA-21 has been associated with glioblastoma resistance to temozolomide, the standard first-line treatment, by regulating the balance between the pro-apoptotic Bax protein and the anti-apoptotic Bcl-2, as well as by influencing Caspase 3 activity." (PMID 39851519, 2025). "A key study found that miR-153 is down-regulated in glioblastoma, with re-expression in cell lines associated with decreased proliferation and increased apoptosis; the researchers further demonstrated that miR-153 directly inhibited anti-apoptosis molecules BCL-2 and MCL-1." (PMID 23335942, 2012). "Despite strong preclinical rationale, direct clinical implementation of strategies targeting the Bcl-2:beclin-1 checkpoint in glioblastoma multiforme has been constrained by several practical barriers." (PMID 41511337, 2025). "Post-siRNA treatment, glioblastoma cells showed resistance to TMZ due to upregulated BCL-2 and TOPO-2, which inhibit apoptosis through NF-kappa B activation." (PMID 40739397, 2025). "We found that BAX, CYCS and CASP3 levels amplified and Bcl‐2 levels reduced in U251 glioblastoma cells to which we applied BA at different doses." (PMID 40318008, 2025). "As it results from the conducted research, blocking the expression of both beclin 1 and Bcl-2 protein completely eliminated the autophagy in anaplastic astrocytoma and glioblastoma multiforme cells." (PMID 39352533, 2025). "Pyruvate kinase M1/2 (PKM/PKM2), a glycolytic regulator, interacted with and phosphorylated Bcl-2 apoptosis regulator (Bcl-2) to upregulate its expression, suppressing apoptosis in glioblastoma cells and promoting NSCLC cell proliferation." (PMID 40508066, 2025). "Under oxidative stress, PKM2 has been found to translocate into mitochondria, where PKM2 interacts with BCL-2 and phosphorylates it at T69, preventing Cul3-based E3 ligase for BCL-2 degradation and consequent cell apoptosis in glioblastoma." (PMID 40612109, 2025).
glioblastoma (continued). "Researchers have designed acid-sensitive bionic nanocarriers based on ApoE peptide-modified erythrocyte membranes for the delivery of Bcl-2/Bcl-xl and Mcl-1 inhibitors to treat glioblastoma (GBM)." (PMID 40420216, 2025). "To verify the effect of BIBF on apoptosis in glioblastoma cells, we analyzed the expression levels of Bax, Bcl-2, caspase-3, and cleaved-caspase-3 using protein blotting." (PMID 39859159, 2025). "In a previous study, our data showed that CUSP9v3 combined with Bcl-2/Bcl-xL inhibition using Navitoclax (ABT-263) resulted in predominantly synergistic antineoplastic activity among different glioblastoma models." (PMID 38396172, 2024). "ZIKV also downregulates Bcl-2, promoting further cell death in glioblastoma cells, highlighting its potential as an effective oncolytic therapy." (PMID 39347716, 2024). "The most frequently observed types of PCD in glioblastoma cells are apoptosis (type I) and autophagy (type II), which are regulated at the molecular level by numerous proteins, including Bcl-2 (apoptosis) and beclin-1 (autophagy)." (PMID 38067099, 2023). "The combination of LY294002 and sorafenib was the most effective in sensitizing Bcl-2-silenced anaplastic astrocytoma and glioblastoma multiforme cells to apoptosis induction." (PMID 38067099, 2023). "Based on these data, we used shRNAs targeting BCL2, Bcl-xL, and MCL-1 anti-apoptotic proteins in stably P21-overexpressing senescent glioblastoma cells, as compared to naïve cells or cells deficient in P21." (PMID 36831620, 2023). "While Zhx1 inhibited the apoptosis of glioblastoma cells by regulating the expression of Bcl2 and Bax and induced early proteinuria and primary glomerular disease by upregulating the Angptl4 expression." (PMID 37452012, 2023). "Together, these results indicated that Chr-A regulates the balance between Bax and Bcl-2, inducing apoptosis of glioblastoma cells in vivo and in vitro." (PMID 37367654, 2023). "Glioblastoma patient samples from our cohort and the TCGA also displayed a correlation between higher IL-11Rα and Bcl-2 gene expression." (PMID 36834778, 2023). "Simultaneous application of LY294002 and sorafenib in anaplastic astrocytoma, as well as in glioblastoma multiforme, affected the co-localization of Bcl-2 and beclin-1, which were distributed around the formed apoptotic bodies." (PMID 38067099, 2023). "BCL-2 mRNA is a predicted and experimentally validated target for miR-21 in several cancers, including breast, lung, and glioblastoma." (PMID 36765584, 2023). "Zafirlukast has been described to cause cell death in many types of tumor cells and the majority of reports link zafirlukast to triggering apoptosis, for example by inducing BCL-2-dependent apoptosis in glioblastoma cell lines." (PMID 35408930, 2022). "4-phenylbutyric acid, 5-aza-2 ́-deoxycytidine and Olea europaea leaf extract induce apoptosis through upregulation of miR-153 targeting Bcl-2, Mcl-1 and Irs2 in glioblastoma." (PMID 36158686, 2022). "The regulation of STAT3 is critical for Bcl-2-interaction cell death suppressor (BIS)-targeted cellular senescence in glioblastoma and ROS-induced senescence in lung fibroblasts." (PMID 36055997, 2022). "The mitochondrial damage caused glioblastoma cells to undergo autophagy preferentially by downregulating the expression of PARL and changing the ratio of BECN1/Bcl‐2 and the process of mitophagy was regulated by the PI3K/Akt/MAPK/mTOR/Ulk1 pathway." (PMID 34799992, 2022). "BCL-2 is a target of various microRNAs, such as miR-181b-5p and miR-18, that acts to overcome temozolomide-induced resistance in glioblastoma cells." (PMID 35804989, 2022).
glioblastoma (continued). "At the same time, curcumin induces an anti-glioblastoma effect by suppression of anti-apoptotic signals, as confirmed by the augmented Bax:Bcl2 ratio in different human glioblastoma cell lines." (PMID 35328780, 2022). "Using siRNA significantly diminishes Bcl-2 expression to induce apoptosis in glioblastoma cells, and promote their sensitivity to taxol chemotherapy." (PMID 34943856, 2021). "It was found that in glioblastoma cells and malignant mesothelioma cells expressing Cx43, a reduced level of expression of antiapoptotic Bcl-2 and Src was observed which promoted carcinogenesis." (PMID 34439975, 2021). "For example, NTSR1 inhibition induces intrinsic apoptosis via downregulation of Bcl-w and Bcl-2 in glioblastoma cells." (PMID 34439758, 2021). "High levels of Mcl-1 mediate BH3-mimetic resistance, suggesting that a dual inactivation of Bcl-2/Bcl-xL and Mcl-1 is necessary for apoptosis of glioblastoma cells." (PMID 34485282, 2021). "In any case, taken together, these data showed a good homogeneity of response in the three glioblastomas, especially concerning the dramatic down modulation of Bcl-2 that is consistent with the apoptotic mechanisms producing the observed cellular damages." (PMID 34959382, 2021). "For instance, Bcl-2 is an anti-apoptotic factor that its up-regulation is in favor of glioblastoma growth and viability." (PMID 34943856, 2021). "RNA interference mediated reduction in BCL-2 or BCL-XL was able to kill glioblastoma cells in culture, and this death was caspase dependant." (PMID 34099897, 2021). "Treatment of glioblastoma cells with simvastatin or lovastatin also produced a consistent decrease in c-Myc, Mcl-1, Bcl-2, and Bcl-xL levels." (PMID 34209035, 2021). "Our data showed that Bcl-2/Bcl-xL inhibition increases the response of glioblastoma cells toward photodynamic therapy." (PMID 34439278, 2021). "Recently, several reports showed STAT3 had vital roles in tumor progression; e.g., it was reported miR-519a enhanced chemosensitivity and promoted autophagy in glioblastoma by targeting the STAT3/Bcl2 signaling pathway." (PMID 33896365, 2021). "RT-qPCR revealed that BCL-2, an antiapoptotic gene, was significantly downregulated both by CisPt and Pt-8AQ in all the treated glioblastoma cells." (PMID 34959382, 2021). "As there were a series of downstream molecules of this pathway involved in proliferation, apoptosis, migration, and invasion of glioblastoma, we examined some of the downstream molecules, including: Cyclin D1, p21, Bcl-2, Bax, MMP-2, and MMP-9." (PMID 32596388, 2020). "Immunoblot analysis revealed that the pro-apoptotic markers BAX and cleaved caspase-3 were increased and the anti-apoptotic marker BCL-2 was decreased in BMAL1-overexpressing glioblastoma cells compared with control cells." (PMID 32231148, 2020). "In glioblastomas, WT1 significantly associates the poor prognostic variables including old age, IDH1 negativity, and high Bcl2 and Ki67 labelling indices." (PMID 32856872, 2020). "Overexpression of onco-miR miR-21 was correlated with downregulation of pro-apoptotic Bax and upregulation of anti-apoptotic Bcl2 and induced apoptosis in glioblastoma." (PMID 32489562, 2020). "It was recently reported that combined treatment with metformin and TMZ overcomes resistance of glioblastoma cells to apoptosis by increasing the ratio of Bax/Bcl-2." (PMID 30446901, 2019). "It was reported that treatment with BH3 mimetic ABT-737 releases the pro-apoptotic Bax protein from its binding partner Bcl-2 and potently induces apoptotic cell death in glioblastoma cells in vitro and in vivo." (PMID 30446901, 2019). "Our results are in line with previous findings in glioblastoma cell lines where high expression level of Cx43 was accompanied by low Bcl-2 expression and high sensitivity to therapies containing taxane agents." (PMID 31766723, 2019).